UHRF1 (ubiquitin like with PHD and ring finger domains 1)
Diseases named in the same sentence as UHRF1 in open-access papers (continued):
Sharing a sentence is not in itself a finding about the gene and the disease.
retinoblastoma (15 papers, 2014 to 2025). A malignant tumor that originates in the nuclear layer of the retina. "UHRF1 overexpression is observed in multiple types of cancer with pRB loss, including retinoblastoma, with loss of UHRF1 capable of reversing the adverse effects associated with pRB loss." (PMID 33003565, 2020). "Moreover, in retinoblastoma cells depleted of UHRF1, it was observed that the chromatin association of DNA ligase IV in response to acute DNA damage was significantly reduced." (PMID 37679817, 2023). "However, the molecular mechanisms underlying tumor-promoting functions of UHRF1 in retinoblastoma still remain elusive." (PMID 29415984, 2018). "These experimental evidences demonstrate that Rb1 inactivation may be implicated in the high expression of UHRF1 in retinoblastoma through deregulated E2F proteins." (PMID 28467809, 2017). "To determine whether UHRF1 or HELLS expression are required for retinoblastoma’s growth, survival, or both, we acquired lentiviral vectors encoding shRNAs to UHRF1 (lenti-UHRF1) and HELLS (lenti-HELLS)." (PMID 25338120, 2014). "In particular, we have identified Uhrf1 and Hells as two genes encoding proteins involved in chromatin remodeling that may be involved in the epigenetic changes observed in retinoblastoma and required for tumor survival." (PMID 25338120, 2014). "Particularly, inhibition of UHRF1, a key epigenetic regulator coordinating DNA methylation and histone modifications, sensitizes retinoblastoma cells to HDAC inhibitors, suggesting novel therapeutic avenues targeting this interplay." (PMID 41150792, 2025). "One retinoblastoma study showed that the targeted depletion of UHRF1 significantly enhances the sensitivity of retinoblastoma cells to a panel of chemotherapeutic agents including etoposide, camptothecin, and carboplatin." (PMID 39051184, 2024). "For instance, in a study in mouse models prone to retinoblastoma, both mRNA and protein levels of UHRF1 were notably high, suggesting its role in tumor initiation and progression." (PMID 39051184, 2024). "The strategies aimed at reducing UHRF1 activity in retinoblastoma cells enhance sensitivity to HDAC inhibitors, offering another potential therapeutic approach by exploiting the interplay between HDACs and UHRF1 in retinoblastoma progression." (PMID 39000021, 2024). "For example, when UHRF1 is depleted in retinoblastoma cells, there is an increase in apoptotic markers including cleaved caspase-3 and PARP1." (PMID 39051184, 2024). "Silencing UHRF1 inhibits cell proliferation and promotes cell apoptosis in retinoblastoma through the PI3K/Akt signaling pathway." (PMID 35035504, 2022). "Etoposide (topoisomerase II inhibitor), camptothecin (topoisomerase I inhibitor), and carboplatin were used for dose–response and time-course studies on control and UHRF1-knockdown Y79 retinoblastoma cells." (PMID 29415984, 2018). "As in many human cancers, retinoblastoma has a high level of UHRF1 expression that contributes to retinoblastoma development." (PMID 29415984, 2018). "UHRF1 (ubiquitin-like with PHD and ring finger domains 1) is highly expressed in various human cancers including retinoblastoma, and associated with tumor-promoting effects such as inhibition of apoptosis and high proliferation." (PMID 29415984, 2018). "In this regard, we examined nuclear factors involved in the repair of etoposide-induced DSBs, and identified XRCC4 as a key mediator regulated by UHRF1 in retinoblastoma cells." (PMID 29415984, 2018). "Similar apoptotic responses upon UHRF1 knockdown were observed for another retinoblastoma cell line, Weri-Rb1." (PMID 29415984, 2018). "As in other human cancers, UHRF1 is highly expressed in retinoblastoma and exerts tumor-promoting effects as demonstrated by impaired colony formation and reduced size of xenografted tumors upon UHRF1 down-modulation in retinoblastoma cells." (PMID 29415984, 2018).
retinoblastoma (continued). "In this study, we demonstrate that high UHRF1 expression in retinoblastoma promotes tumor cell survival against genotoxic insults by enhancing DNA repair and consequently reducing apoptotic cell death." (PMID 29415984, 2018). "Here, we show that stable knockdown of UHRF1 renders retinoblastoma cells sensitized to conventional chemotherapeutic drugs such as etoposide and camptothecin, resulting in enhanced DNA damage and apoptotic cell death." (PMID 29415984, 2018). "The XRCC4 downregulation upon UHRF1 knockdown was observed in other retinoblastoma cell lines (Weri-Rb1 and SO-Rb50) and 293T cells, and occurred at the transcript level." (PMID 29415984, 2018). "UHRF1-depleted retinoblastoma cells showed a clear increase in sensitivity to the two topoisomerase inhibitors, whereas only modest increase in sensitivity to carboplatin was observed at high doses or longer treatment." (PMID 29415984, 2018). "Lentiviral transduction of UHRF1 shRNA efficiently reduced the UHRF1 protein level in retinoblastoma cell lines while the expression level of DNMT family proteins was not concomitantly changed." (PMID 28467809, 2017). "We also performed MeDIP-sequencing to uncover any potential effects of UHRF1 knockdown on DNA methylation in retinoblastoma by genome-wide examination of relative methylation differences between control and UHRF1 knockdown Y79 cells." (PMID 28467809, 2017). "In summary, we investigated the role of UHRF1 in establishment and maintenance of DNA methylome in retinoblastoma, using mouse models and human retinoblastoma cells." (PMID 28467809, 2017). "As in human retinoblastoma, UHRF1 is highly expressed in mouse retinoblastoma which is known to recapitulate many characteristics of human retinoblastoma." (PMID 28467809, 2017). "Nevertheless, UHRF1 was shown to have tumor-promoting functions in retinoblastoma development as demonstrated by impaired colony formation and reduced size of xenografted tumors upon UHRF1 knockdown in retinoblastoma cells." (PMID 28467809, 2017). "Our study on the functions of UHRF1 in DNA methylome regulation and contribution of global methylation changes to retinoblastoma tumorigenesis provides a new insight into retinoblastoma biology." (PMID 28467809, 2017). "In this study, we investigated the functions of UHRF1 in the regulation of DNA methylation in retinoblastoma and assessed the contribution of global DNA methylation changes to retinoblastoma tumorigenesis." (PMID 28467809, 2017). "Although UHRF1 has modest effects on DNA methylation in retinoblastoma cells and mouse tumors, there are distinct features in human retinoblastoma methylomes both globally and in loci-specific manners." (PMID 28467809, 2017). "The high UHRF1 expression was accompanied by a high level of E2F1 expression which was also observed in retinoblastoma by others." (PMID 28467809, 2017). "Another related study from our laboratory also indicates that UHRF1 down-regulation is beneficial to augment the therapeutic efficacy of retinoblastoma treatment (unpublished data)." (PMID 28467809, 2017). "Since UHRF1 expression is high and differential DNA methylation exists in retinoblastoma as compared with normal retina, we next investigated the effects of UHRF1 knockdown on global and gene-specific methylation in retinoblastoma cells." (PMID 28467809, 2017). "A recent study showed that UHRF1 is highly expressed in a subset of human retinoblastoma and down-regulation of UHRF1 significantly reduces the size of retinoblastoma tumors grown in orthotopic xenograft models." (PMID 28467809, 2017). "Downregulation of XRCC4 by UHRF1 depletion sensitized retinoblastoma cells to more chemotherapy." (PMID 32258128, 2020). "The difference may be associated with using different cell types and genotoxic agents, but points out that UHRF1 employs a different mechanism in retinoblastoma cells to promote cell survival against the potent DSB inducer." (PMID 29415984, 2018).
retinoblastoma (continued). "Taken together, these results present a new mechanistic insight into how UHRF1 mediates its tumor-promoting functions in retinoblastoma, and also provide a basis for UHRF1 targeting to improve the efficacy of current chemotherapy for retinoblastoma treatment." (PMID 29415984, 2018). "Third, UHRF1 down-modulation sensitizes retinoblastoma cells to standard chemotherapeutic drugs." (PMID 29415984, 2018). "Given the well-documented roles of UHRF1 in DNA methylation, high expression of UHRF1 in retinoblastoma was hypothesized to have a critical impact on the arrangement of retinoblastoma methylome and tumorigenesis processes." (PMID 28467809, 2017). "We examined human primary retinoblastoma and normal retina (NR) for UHRF1 expression." (PMID 28467809, 2017). "In addition to primary tumors, we also verified the results in retinoblastoma cell lines (Y79, Weri-Rb1, and SO-Rb50), demonstrating that UHRF1 is highly expressed at both protein and transcript levels." (PMID 28467809, 2017). "Therefore, we investigated if high expression of UHRF1 can decrease global DNA methylation levels in mouse retinoblastoma models." (PMID 28467809, 2017). "In this study, we used murine retinoblastoma models where we can monitor different levels of UHRF1 expression according to the extent of Rb1 inactivation which may be a physiological cause for high UHRF1 expression in retinoblastoma." (PMID 28467809, 2017). "Unlike what has been predicted based on its well-known functions in DNA methylation, our comprehensive methylation analyses revealed that the high level of UHRF1 expression in retinoblastoma has little effect on the establishment and maintenance of retinoblastoma methylome." (PMID 28467809, 2017). "In this regard, high expression of three DNMT family proteins in human primary retinoblastoma and cell lines may account for the differences in the regulation of retinoblastoma methylomes, reducing the dependency on UHRF1 for the regulation of DNA methylation." (PMID 28467809, 2017). "Indeed, qPCR analysis of primary human retinoblastoma tissue showed that UHRF1 and HELLS are significantly upregulated in some retinoblastomas." (PMID 25338120, 2014). "Interestingly, our previous analysis of the epigenetic landscape of human retinoblastoma identified UHRF1 as a gene epigenetically deregulated in retinoblastoma." (PMID 25338120, 2014). "In an attempt to investigate how UHRF1 contributes to retinoblastoma development, we tested a possibility that high UHRF1 expression in retinoblastoma cells may endow the cells with the resistance against chemotherapeutic drugs used for retinoblastoma treatment in clinical settings." (PMID 29415984, 2018). "Therefore, high UHRF1 expression may promote retinoblastoma development primarily through its other functions, rather than deregulation of DNA methylation." (PMID 28467809, 2017). "However, our genome-wide DNA methylation study uncovers that UHRF1 down-modulation in retinoblastoma cells exerts minor effects on the existing methylation patterns at both bulk genome and individual gene loci, suggesting that retinoblastoma methylome is primarily maintained by other mechanisms." (PMID 28467809, 2017). "Considering that normal retina does not express UHRF1, our findings suggest that local UHRF1 targeting in affected lesions may be promising for a novel retinoblastoma therapy without a risk of systemic complications in DNA methylation." (PMID 28467809, 2017). "Indeed, several studies identified UHRF1 as a direct target of E2F1 in various cell systems, and genetic disruption of E2f1 or E2f3 in a murine retinoblastoma model was shown to ablate UHRF1 expression in Rb1-knockout retinae that would otherwise exhibit high UHRF1 expression." (PMID 28467809, 2017). "This study presents two novel tumor‐promoting functions of UHRF1 in retinoblastoma (RB)." (PMID 31782885, 2020).
retinoblastoma (continued). "To compare the expression patterns of UHRF1 and XRCC4, we used two serial retinoblastoma sections for UHRF1 and XRCC4 immunostaining." (PMID 29415984, 2018). "As in retinoblastoma cells, UHRF1 knockdown in 293T cells induced more intense apoptosis upon etoposide treatment, and overexpression of XRCC4 in UHRF1-depleted cells attenuated the apoptosis." (PMID 29415984, 2018). "All of these lentiviruses efficiently knocked down UHRF1 and HELLS in the 293T cell line and retinoblastoma cell lines." (PMID 25338120, 2014). "UHRF1 and HELLS knockdown in both control and retinoblastoma cell lines led to a significant reduction in colonies formed compared to the lenti-GFP controls." (PMID 25338120, 2014). "For instance, numerous studies showed that the presence of many dysregulation CRs (e.g., UHRF1, DNMT1, EZH2, BMI1 and HELLS) might lead to an abnormal epigenetic landscape in retinoblastoma (RB), which might be associated with tumorigenesis and malignant progression." (PMID 36318256, 2023). "The uHRF1-mediated PI3K/Akt signaling pathway downregulates the bcl-2/Bax expression ratio and promotes caspase-9 expression, which can inhibit the proliferation of retinoblastoma cells and promote apoptosis." (PMID 35656341, 2022). "We found that UHRF1-depleted retinoblastoma cells can recognize DNA damages normally but have markedly low expression of XRCC4 (X-ray repair cross complementing 4) among the components of nonhomologous end-joining (NHEJ) repair complex." (PMID 29415984, 2018). "Taken together, our genome-wide methylation analysis in Y79 retinoblastoma cells revealed that UHRF1 does not exert much effect on the overall methylation patterns, unlike what has been predicted based on the studies in other cancer cells." (PMID 28467809, 2017). "Unlike most human cancers where the mechanisms driving the UHRF1 overexpression are unclear, retinoblastoma was proposed to have a clear genetic alteration that can be connected with high expression of UHRF1." (PMID 28467809, 2017). "Like UHRF1, HELLS was also epigenetically upregulated in human retinoblastoma." (PMID 25338120, 2014). "At the protein level, we identified overexpression of UHRF1 and HELLS in a subset of the human retinoblastoma tumors and in all the human retinoblastoma cell lines analyzed (RB355, Weri, and Y79) when compared to normal fetal retina (FW19) and normal human fibroblasts (BJ)." (PMID 25338120, 2014). "Interestingly, researching the data from our previous integrative analysis of human retinoblastoma, we found that the human orthologs, UHRF1 and HELLS, were both epigenetically upregulated in human retinoblastoma." (PMID 25338120, 2014). "Here, we report that downmodulation of UHRF1 (ubiquitin‐like with PHD and RING finger domains 1) in retinoblastoma (RB) cells increases the sensitivity to histone deacetylase (HDAC) inhibitors, augmenting apoptotic cell death." (PMID 31782885, 2020). "Unpublished studies from our lab using genetic engineered mouse models of retinoblastoma also indicate that UHRF1 overexpression is required for the epigenetic changes that drive retinoblastoma tumor progression and in the absence of UHRF1, retinoblastoma tumors fail to form." (PMID 33003565, 2020). "Of note, XRCC4 expression is detectable in human normal retina unlike the case of UHRF1, and our data suggest that high UHRF1 expression during retinoblastoma tumorigenesis may further augment the XRCC4 expression in tumors." (PMID 29415984, 2018). "However, our results revealed that UHRF1 depletion in retinoblastoma cells does not affect the recognition of DNA damages generated by etoposide treatment, and UHRF1 does not appear to be recruited to DSBs marked by γH2AX." (PMID 29415984, 2018).
retinoblastoma (continued). "Conversely, overexpression of UHRF1 increased the XRCC4 expression and stable knockdown of XRCC4 sensitized retinoblastoma cells to etoposide treatment, suggesting that XRCC4 is a key mediator for the drug sensitivity upon UHRF1 depletion in retinoblastoma cells." (PMID 29415984, 2018). "Therefore, tumor-promoting effects of UHRF1 in retinoblastoma are likely to involve other functions of UHRF1 rather than its role in DNA methylation." (PMID 28467809, 2017). "This suggests that other nuclear factors rather than UHRF1 may play a key role in reprograming methylomes in retinoblastoma." (PMID 28467809, 2017). "This suggests that tumor-promoting functions of UHRF1 in retinoblastoma are largely independent of its role in DNA methylation, and the potential role for UHRF1 in tumor methylome regulation may be tumor type-specific." (PMID 28467809, 2017). "As higher levels of γH2AX were detected in UHRF1-knockdown cells following the prolonged etoposide treatment for 24 h, we suspected that the observation in other cancer cell lines may not hold true for retinoblastoma cells." (PMID 29415984, 2018). "We also found that Uhrf1 (ubiquitin-like, containing PHD and RING finger domains 1) and Hells (helicase, lymphoid specific) proteins are overexpressed in retinoblastoma and may be responsible for the epigenetic changes seen in retinoblastoma and required for tumor survival." (PMID 25338120, 2014).
esophageal squamous cell carcinoma (13 papers, 2016 to 2025). Esophageal squamous cell carcinoma (ESCC) is a type of esophageal carcinoma (EC) that can affect any part of the esophagus, but is usually located in the upper or middle third. "Recently, transgenic overexpression of UHRF1 in normal zebrafish hepatocytes was shown to induce DNA hypomethylation, and vector-mediated UHRF1 overexpression in esophageal squamous cell carcinoma (ESCC) cell lines was reported to cause global hypomethylation." (PMID 28467809, 2017). "The ubiquitin-like with plant homeodomain and ring finger domains 1 (UHRF1) regulates cancer signaling pathways in esophageal squamous cell carcinoma (ESCC) by influencing the PI3K/Akt/mTOR pathway, crucial for tumor growth and resistance to therapies." (PMID 38813086, 2024). "In esophageal squamous cell carcinoma (ESCC), resistance to radiation therapy is directly associated with overexpression of UHRF1." (PMID 29899856, 2018). "Similarly, PHD-containing protein UHRF1 regulates esophageal squamous cell carcinoma via the PI3K/Akt/mTOR pathway, facilitated by the demethylation of tumor suppressor genes." (PMID 38813086, 2024). "Additionally, UHRF1’s regulation of the PI3K/Akt/mTOR pathway in esophageal squamous cell carcinoma further illustrates the extensive impact of these proteins on cancer pathophysiology, offering novel insights into potential therapeutic targets." (PMID 38813086, 2024). "Moreover, a recent study reported that UHRF1 silencing could increase the radiosensitivity of ESCC (esophageal squamous cell carcinoma) through the inhibition of the PI3K/Akt/mTOR signaling pathway." (PMID 37630248, 2023). "A previous study tested the expression of UHRF1 by immunohistochemistry in specimens of esophageal squamous cell carcinoma (ESCC) patients who treated with radiotherapy, in which it was revealed that UHRF1 was significantly overexpressed in ESCC specimens." (PMID 31428652, 2019). "Nonetheless, the relationship between UHRF1, LINE-1 methylation level, and clinical outcome in esophageal squamous cell carcinoma (ESCC) remains unclear." (PMID 27507047, 2016). "In esophageal squamous cell carcinoma, a distinct model was proposed, in which, the lncRNA LUCAT1 binds DNMT1 to protect it from ubiquitination, while LUCAT1 knock-down promotes ubiquitination of DNMT1 through UHRF1 (Ubiquitin-Like PHD and RING Finger Domain-Containing Protein 1)." (PMID 35292092, 2022).